LTBR (lymphotoxin beta receptor)
Diseases named in the same sentence as LTBR in open-access papers (continued):
Sharing a sentence is not in itself a finding about the gene and the disease.
liver cancer (4 papers, 2016 to 2025). An epithelial or non-epithelial malignant neoplasm that arises from the liver. "This analysis showed a similar trend to the effect observed with HOIP expression in liver cancer patients with high LTβR expression." (PMID 39215104, 2024). "The role of LUBAC and linear ubiquitin in liver cancer has previously been reported by us and others and the impact of LTβR signaling in hepatocarcinogenesis has also been studied." (PMID 39215104, 2024). "IL-8 and CCL20 were induced by LTβR stimulation in two different liver cancer cell lines (HLE and JHH4) and in one HNSCC line (HSC3)." (PMID 39215104, 2024). "We next analyzed expression levels of LTβR in primary samples obtained from liver cancer patients by immunohistochemistry." (PMID 39215104, 2024). "High LTβR expression negatively correlates with overall survival in patients with liver cancer, lung adenocarcinoma, RCC (clear cell subtype), and HNSCC." (PMID 39215104, 2024). "A total of 14 liver cancer patients were stratified into high and low LTβR expression based on staining intensity for LTβR." (PMID 39215104, 2024). "We further demonstrate LTβR signalling in human liver cancer cell lines to be a regulator of Notch, pAKTser473 and β-catenin." (PMID 26206664, 2016). "To confirm the novel role of LTβR signalling in the pathogenesis of human liver cancers, particularly ICC, we first screened by flow cytometry several human liver tumour cell lines for LTβR expression." (PMID 26206664, 2016). "Our efforts are focused on the role of LTβR signalling in modulating oncogenesis using two pathologically distinct models of human liver cancer." (PMID 26206664, 2016). "The LTβR is broadly expressed in human liver cancer cell lines and contributes to maintaining AKT activation and the accumulation of NICD." (PMID 26206664, 2016). "Moreover, high LTβR expression is considered a poor prognostic marker in liver cancer patients, an observation which is corroborated by the bioinformatic analysis we present here." (PMID 39215104, 2024). "Additionally, we investigated the impact of another LUBAC component, HOIL-1, which positively regulates NF-κB signaling, on the overall survival of liver cancer patients with high LTβR expression." (PMID 39215104, 2024). "Moreover, specific LTβR-mediated molecular events were investigated in human liver cancer cell lines and through transcriptional analyses of samples from patients with intrahepatic cholangiocarcinoma (ICC)." (PMID 26206664, 2016). "Intriguingly, in liver cancer patients with high LTβR expression, high expression of LUBAC correlates with poor prognosis, providing clinical relevance for LUBAC-mediated inflammatory LTβR signaling." (PMID 39215104, 2024). "Moreover, hepatocyte-specific knock-out of canonical ikkβΔhep and LTβR signaling (LtβRΔhep mice) confirmed that LTβR and NF-κB signaling in hepatocytes facilitated CD-HFD-induced liver cancer." (PMID 27072576, 2016). "This analysis suggests that LTβR signaling may not primarily affect immune cells in the context of liver cancer but rather the tumor cells themselves." (PMID 39215104, 2024).
lung adenocarcinoma (4 papers, 2019 to 2024). A carcinoma that arises from the lung and is characterized by the presence of malignant glandular epithelial cells. "LTBR+ TAMs are associated with lung adenocarcinoma stages, immunotherapy failure, and poor prognosis." (PMID 39429877, 2024). "By differential expression analysis and LASSO logistic regression analysis we constructed an 8-gene (IKBKB, LTBR, MIF, PPARD, PPIA, PSME3, S100A6, SEMA4B) based risk score model to predict lymph node metastasis in lung adenocarcinoma." (PMID 34109216, 2021). "Gene expression profiles of CD40, BAFFR, RANK and LTβR had similar patterns in the LUSC (lung squamous cell carcinoma) and LUAD (lung adenocarcinoma) subgroups analyzed and both were similar to control samples." (PMID 31137630, 2019).
non-small cell lung carcinoma (4 papers, 2019 to 2024). A group of at least three distinct histological types of lung cancer, including non-small cell squamous cell carcinoma, adenocarcinoma, and large cell carcinoma. "At the same time, LTβR is amplified or overexpressed in HNSCCs of the larynx or oral cavity and increased LTβR expression is associated with a worse overall survival in patients with non-small-cell lung cancer." (PMID 33917839, 2021). "Immune system-related receptors CD40 (tumor necrosis factor receptor superfamily member 5), BAFFR (tumor necrosis factor receptor superfamily member 13C), and LTβR (tumor necrosis factor receptor superfamily member 3) play a pivotal role in non-small-cell lung cancer (NSCLC)." (PMID 34604057, 2021).
Arthritis (3 papers, 2009 to 2019). Inflammation of a joint. "With regards to LTBR, LTBR activated NFkB and blockade of LTBR impaired humoral immune response and ameliorated arthritis in the animal model." (PMID 31443559, 2019). "A protective effect of polyclonal human IgG used as a control protein in experiments to determine the efficacy of LTβR-Ig in collagen-induced arthritis was reported." (PMID 19222863, 2009). "Thus, upregulated LTBR potentially activates humoral immunity and facilitated arthritis development." (PMID 31443559, 2019).
cerebral malaria (3 papers, 2008 to 2017). A sequestration of Plasmodium falciparum in the brain, which can cause coma and/or seizures. "We previously reported increased monocyte recruitment into the spleen in an experimental model of cerebral malaria following treatment of mice with the anti-LTβR mAb (LLTB2), and that this treatment protected mice from disease." (PMID 21998581, 2011). "Interestingly, the strong increase in brain CD8+ T cells seen in wild type or TNF deficient mice that develop cerebral malaria was essentially absent in PbA-infected LTβR or LTβ deficient mice." (PMID 18612394, 2008). "The present data demonstrate that interruption of LTβR signaling abrogates the microvascular disease leading to fatal ECM, which sheds a new light on the pathogenesis of cerebral malaria." (PMID 18612394, 2008). "Interestingly, no protection from experimental cerebral malaria was afforded by treatment with the anti-LTβR (3C8) mAb (Randall and Engwerda, unpublished), again emphasising the functional differences between LLTB2 and 3C8 anti-LTβR mAbs." (PMID 21998581, 2011).
chronic obstructive pulmonary disease (3 papers, 2022 to 2024). A chronic and progressive lung disorder characterized by the loss of elasticity of the bronchial tree and the air sacs, destruction of the air sacs wall, thickening of the bronchial wall, and mucous accumulation in the bronchial tree. "Additionally, a recent study found that LIGHT, LTαβ, and signaling pathways associated with LTβR were upregulated in lung biopsies from patients with smoking-associated chronic obstructive pulmonary disease." (PMID 35604387, 2022). "Correspondingly, blockade of LIGHT with decoy LTβR-Fc suppressed lung fibrosis and inflammation induced by chronic exposure to cigarette smoke in a mouse model of chronic obstructive pulmonary disease." (PMID 35604387, 2022). "Recently, it was reported that WNT/β-catenin signaling can be induced by blockage of LTβR signaling in ATII cells, which leads to enhanced lung alveolar regeneration in chronic smoking-induced lung diseases such as chronic obstructive pulmonary disease (COPD)." (PMID 35130980, 2022).
colon carcinoma (3 papers, 2021 to 2025). "Additionally, LTβR agonist antibodies effectively inhibited tumor growth in colon cancer." (PMID 40883295, 2025).
fibrosarcoma (3 papers, 2022 to 2023). A malignant mesenchymal fibroblastic neoplasm affecting the soft tissue and bone. "In contrast, a recent report showed that tumors forming in mice inoculated with a fibrosarcoma cell line developed TA-HEVs surrounded by both CD8+ T cells and B cells with LTβR agonist antibodies alone." (PMID 36704666, 2022). "The extensive TA-HEV networks that form in MCA-induced fibrosarcomas treated with LTβR agonist alone in the absence of Treg depletion and the lack of tumour control thereof are a clear testament to this notion." (PMID 37287625, 2023). "Notably, we characterized a Treg-tumor cell-specific interaction mediated by the ligand Lymphotoxin Beta (LTB) and its receptor lymphotoxin beta receptor (LTBR), which is required for fibrosarcoma and hepatocellular carcinoma tumor formation." (PMID 35853872, 2022).
lupus (3 papers, 2019 to 2025). "A recent study reported that LTβR protein is localized to renal tubular epithelial cells (RTECs), and LTβR blockade significantly improved renal function in a murine lupus model." (PMID 39707217, 2024). "Indeed, LTB-LTBR signaling is up-regulated in human kidneys with inflammatory glomerulonephritis, and LTBR blockade in mouse lupus models improves kidney function." (PMID 41282674, 2025).
malaria (3 papers, 2009 to 2017). Malaria is a serious and sometimes fatal disease caused by a parasite that commonly infects a certain type of mosquito which feeds on humans. "Nevertheless, these LTβR-deficient mice are even more resistant to blood-stage malaria of P. chabaudi than the corresponding control mice." (PMID 25408684, 2014). "These analyses confirmed suppression of Sult2a mRNA levels by blood stage malaria in BALB/c mice on days 8 and 11 p.i. as previously shown in C57BL/6 and LTβR-/- mice." (PMID 19341445, 2009).
Obesity (3 papers, 2013 to 2021). Accumulation of substantial excess body fat. "In conclusion, in patients with obesity and type 2 diabetes, insulin infusion leads to a suppression of the expression of IL-4, ADAM-33, LIGHT, and LTBR in parallel with a reduction in plasma NOM, TGFβ, MCP-1, and MMP-9 concentrations." (PMID 25642424, 2015).
acute myeloblastic leukemias (2 papers, 2023). "Lymphotoxin α1β2 expression in acute myeloblastic leukemias (AMLs) and therapeutic effect of lymphotoxin beta receptor (LTβR) blocking." (PMID 36912771, 2023).
B-cell lymphoma (2 papers, 2014 to 2024). "Using transgenic mouse model which displayed an aggressive B-cell lymphoma phenotype, LTβR signalling has been shown to collaborate with CCR7 signaling to maintain T-cell and B-cell localization within the lymphoid microenvironment hence contribution to lymphomagenesis." (PMID 25211095, 2014).
bladder cancer (2 papers, 2015 to 2022). "The role of LT signaling in bladder infection has not been previously investigated, although increased LTβR expression has been described in chronic cystitis and in bladder cancer in humans." (PMID 35845169, 2022).
bladder infection (2 papers, 2015 to 2022). "We aimed to identify a potential causal relationship between cystitis, LTβR signaling and BCa development." (PMID 25369740, 2015). "Both LTβR mRNA and protein were upregulated in BCa and cystitis compared to the healthy group (P<0.05)." (PMID 25369740, 2015). "Positive staining of the LTβR protein (69.8%) in the BCa group was higher than that in healthy bladder mucosa one (13.3%), similarly to the cystitis (90.0%) group." (PMID 25369740, 2015). "It is unknown whether LTβR, as an inflammatory factor receptor, is the key molecule that links cystitis to BCa, or only acts upstream of NF-κB." (PMID 25369740, 2015).
cholangiocarcinoma (2 papers, 2016 to 2018). A carcinoma that arises from the intrahepatic biliary tree (intrahepatic cholangiocarcinoma) or from the junction, or adjacent to the junction, of the right and left hepatic ducts (hilar cholangiocarcinoma). "We found that LTβR was widely expressed by all four cholangiocarcinoma cell lines (Oz, KMBC, HuCCT1 and Mz-ChA-1) we tested, as well as by two HCC cell lines Huh1 and HLE." (PMID 26206664, 2016). "However, given the inflammatory aetiology of cholangiocarcinoma, the investigation of inflammation mediated through the LTβR, and its possible collaboration with molecular events to alter cell fate in the liver, may prove a rich avenue for further study." (PMID 26206664, 2016).
chronic cystitis (2 papers, 2015 to 2022). Recurrent infections of the urinary bladder. "In the present study, we investigated the expression of LTβR pathway-related genes and proteins in BCa, chronic cystitis and healthy bladder mucosa tissues." (PMID 25369740, 2015). "The expression of the LTβR gene in the BCa and the chronic cystitis groups was higher than that observed in the healthy bladder mucosa group, as revealed by Mann-Whitney U tests (both, P<0.05)." (PMID 25369740, 2015). "In addition, our early research demonstrated that the protein expression of LTβR is positively correlated to that of p-p65 and p52 in chronic cystitis tissues." (PMID 25369740, 2015). "The correlation between LTβR and NF-κB in BCa was similar to that observed in chronic cystitis, which suggests that BCa may be related to inflammation." (PMID 25369740, 2015). "The MD of the LTβR protein in the BCa group was significantly higher than that observed in the healthy group, as shown by a Student-Newman-Keuls test (P<0.05), similarly to the comparison between the chronic cystitis and the healthy group (P<0.05)." (PMID 25369740, 2015). "Weak to no LTβR protein expression was detected in healthy bladder mucosa, while positive staining was observed in the cytoplasm and nucleus of chronic cystitis and BCa tissues." (PMID 25369740, 2015).
chronic myeloid leukemia (2 papers, 2021). "Similarly, LTβR deficiency reduced the number of leukemic stem cells and prolonged their survival in a murine model of chronic myeloid leukemia, supporting the idea that LTβR signaling in hematopoietic and leukemic stem cells mediates similar effects." (PMID 33917839, 2021). "LTβR deficiency reduces the numbers of LSCs and prolongs survival in a murine chronic myeloid leukemia (CML) model." (PMID 33594067, 2021). "Indeed, LIGHT/LTβR signaling maintains and expands the pool of LSCs in a murine model of chronic myeloid leukemia (CML) and promotes disease progression." (PMID 33594067, 2021).
Crohn disease (2 papers, 2021 to 2025). A gastrointestinal disorder characterized by chronic inflammation involving all layers of the intestinal wall, noncaseating granulomas affecting the intestinal wall and regional lymph nodes, and transmural fibrosis. "The lymphotoxin β receptor (LTβR), is a key member of the TNF receptor superfamily encoded by the LTBR/TNFRSF3 on chromosome 12, in a susceptibility locus associated with Crohn’s disease in large-scale human genetic studies." (PMID 41030453, 2025).
emphysema (2 papers, 2025 to 2026). "For mice exposed to chronic cigarette smoke, a soluble LTβR protein that inhibits TNFSF14-LTβR interaction ameliorates tertiary lymphoid structures, damage-associated transitional epithelial cells, fibrosis, and emphysema, all of which can be post-acute sequelae of pneumonia." (PMID 41542776, 2026). "For instance, in a mouse model of COPD, elevated expression of LTβR ligands promotes epithelial cell apoptosis via activation of the noncanonical NFκB pathway, leading to emphysema, collagen deposition, and muscle wasting, which could be reverted by blocking LTβR signaling." (PMID 40815083, 2025).
influenza (2 papers, 2026). An acute viral infection of the respiratory tract, occurring in isolated cases, in epidemics, or in pandemics; it is caused by serologically different strains of viruses (influenzaviruses) designated A, B, and C, has a 3-day incubation period, and usually lasts for 3 to 10 days. "The observations that interrupting TNFSF14 or delivering LTβR-deficient AMs can be lifesaving during pneumococcal superinfection of influenza-infected mice suggest that AMs do something in these superinfected lungs that is profoundly helpful." (PMID 41542776, 2026). "Thus, TNFSF14 was sufficient for AM death, and both TNFSF14 and LTβR were necessary for the AM death observed during influenza infection." (PMID 41542776, 2026). "TNFRSF14 deficiency did not affect AM numbers, but LTβR deficiency prevented AM loss during influenza infection." (PMID 41542776, 2026). "TNFSF14 associates with viral infections other than influenza, so interrupting TNFSF14/LTβR signaling may have broader applicability for preventing bacterial superinfections secondary to respiratory viruses." (PMID 41542776, 2026). "After identifying the TNFSF14/ LTβR pathway as mediating AM death during influenza infection, the authors asked whether the pathway contributes to bacterial superinfection severity." (PMID 41542776, 2026). "During influenza infection, most of the apoptotic AMs stained positive for TNFRSF14 and/or LTβR." (PMID 41542776, 2026).
influenza pneumonia (2 papers, 2022 to 2026). "The remaining three genes, PTGER4, TNFRSF1A, and LTBR displayed mixed directions of expression relative to the pneumonia risk increasing allele when annotating individual SNPs with eQTLs depending on the tissue considered." (PMID 35768473, 2022).
kidney cancer (2 papers, 2024 to 2026). Primary or metastatic malignant neoplasm involving the kidney. "LTβR-driven signaling mediators are considered as a prognostic factor in some cancer types, such as liver, head/neck and kidney cancer." (PMID 39215104, 2024).
liver fibrosis (2 papers, 2021 to 2024). "To better understand the effects of LIGHT on liver fibrosis, we used LTβR-Ig to block LIGHT in vivo and performed immunohistochemical staining, Sirius red staining, and western blotting to measure the level of αSMA and fibrosis in liver tissue samples." (PMID 33654222, 2021). "Our results suggest that LIGHT promotes liver fibrosis by binding to LTβR to activate the phosphorylation of JNK." (PMID 33654222, 2021). "To determine whether LIGHT bound to HVEM and/or LTβR in the context of liver fibrosis, we transfected RAW264.7 cells with siRNAs." (PMID 33654222, 2021). "Tumor necrosis factor superfamily 14 (TNFSF14), highly expressed in the context of fibrosis, binds to the lymphotoxin β receptor (LTβR) and activates JNK signaling, thereby regulating TGF-β1 expression, which can contribute to liver fibrosis in vitro." (PMID 39267721, 2024). "Therefore, LIGHT bound to LTβR but not HVEM in RAW264.7 cells to induce the expression of TGF-β1 and αSMA and subsequently induce liver fibrosis." (PMID 33654222, 2021).
lung carcinoma (2 papers, 2019 to 2024). "Cumulatively, our findings suggest that the activation of LTβR-dependent signaling upon cholesterol depletion enhances a pro-inflammatory response and promotes interactions of A549 lung cancer and endothelial cells with diverse types of immune cells." (PMID 31878945, 2019). "Previous studies revealed that human lung carcinoma A549 cells are suitable to study LTβR signaling in vitro." (PMID 31878945, 2019). "To confirm our observations, we measured the expression of selected genes in another lung cancer cell line H2228, which expresses lower levels of LTβR as compared with A549 cells." (PMID 31878945, 2019). "After confirming LTBR knockout efficiency, LTBRcKO mice and the control (Ctrl) mice were intratracheally instilled with Lewis lung carcinoma (LLC) cells to establish an orthotopic lung cancer model." (PMID 39429877, 2024).